TXNIP (thioredoxin interacting protein)
Diseases named in the same sentence as TXNIP in open-access papers (continued):
Sharing a sentence is not in itself a finding about the gene and the disease.
Sepsis (continued). "The results showed that the mRNA levels of IL-18, IL-1β, and procaspase-1 decreased after knockdown of USP5 in LPS-induced sepsis cell model, and overexpressed TXNIP in USP5 knockdown cells could upregulate the inflammatory factors." (PMID 37534934, 2023). "Although our study suggests that the knockdown USP5 could be an effective method for alleviating sepsis-induced liver injury by reducing TXNIP stability, several limitations should be considered." (PMID 37534934, 2023). "miR-25-5p can improve brain injury caused by sepsis by inhibiting the thioredoxin-interacting protein TXNIP/NLRP3 pathway; reducing the levels of TXNIP, NLRP3, and cleaved caspase-1; and inhibiting the expression of inflammatory factors (such as IL-6, IL-1β, and TNF-α and peroxide)." (PMID 37629199, 2023). "The present study showed that TXNIP knockdown significantly inhibited hippocampal microglia activation in the sepsis mice, while the NLRP3 and cleaved caspase-1 protein expression levels and the inflammatory factors, IL-1β and IL-18, were significantly reduced in the hippocampus." (PMID 35571246, 2022). "Therefore, the present study was aimed at elucidating the effects of TXNIP knockdown on sepsis-induced brain injury and cognitive decline in mice." (PMID 35571246, 2022). "In addition, upregulated PPARγ inhibited the expression of the TXNIP/NLRP3 signaling pathway by reducing ROS-induced injury in the liver during sepsis, which further reduced NLRP3-mediated pyroptosis and the inflammatory response." (PMID 35136484, 2022). "Consequently, the present study was aimed at evaluating the effects of TXNIP knockdown on sepsis-induced brain injury and cognitive impairment and the related molecular mechanism." (PMID 35571246, 2022). "Therefore, exosomal miR‐93/TXNIP signalling plays a crucial role in the progress of sepsis‐induced AKI, which provides potential targets for the treatment of AKI." (PMID 33745232, 2021). "In conclusion, our data suggested that miR-30c-5p negatively controlled the NLRP3 signal pathway-related pyroptosis and sepsis-induced injury via TXNIP, indicating that this axis might be a positive therapeutic target for the patient with SAKI." (PMID 32892306, 2021). "Therefore, targeting USP5/TXNIP may be an important therapeutic strategy for sepsis-mediated liver injury." (PMID 37534934, 2023). "In conclusion, this study found that ceramide-mediated endothelial pyroptosis depends on the activation of ROS-dependent TXNIP/NLRP3/GSDMD signalling, and TXNIP inhibition may provide an important adjuvant therapeutic approach for alleviating vascular endothelial injury in sepsis and other diseases." (PMID 36517743, 2022). "Our findings further support this by demonstrating that TN13, which targets the TXNIP-p38 MAPK axis, effectively suppresses inflammatory responses and improves survival in sepsis and ARDS models." (PMID 40142612, 2025). "Next, we identified TXNIP deubiquitination, mediated by the deubiquitinating enzyme USP5, as a novel mediator of sepsis-induced liver injury." (PMID 37534934, 2023). "Our results indicated that increased expression of PPARγ reduced ROS levels and inhibited the TXNIP/NLRP3 signaling pathway, resulting in decreased pyroptosis and reduced liver dysfunction during sepsis." (PMID 35136484, 2022). "In conclusion, the current findings demonstrated that the activation of PPARγ reduced ROS levels and inhibited the TXNIP/NLRP3 signaling pathway to decrease pyroptosis and reduce liver damage during sepsis." (PMID 35136484, 2022). "We also observed that the apoptotic rate of the hippocampal neurons in the TXNIP knockdown group was significantly lower than that of the sepsis mice without TXNIP knockdown." (PMID 35571246, 2022). "The data showed a marked upregulation in the expression levels of TXNIP, NLRP3, caspase-1, and IL-1β, suggesting that the NLRP3 inflammasome may contribute to liver dysfunction during sepsis." (PMID 35136484, 2022).
Sepsis (continued). "The effect of the NLRP3 inflammasome on sepsis brain injury has been preliminarily studied in the CLP-induced mouse model, but the role of its regulatory protein TXNIP in the sepsis brain injury and the effects on the NLRP3 inflammasome remain unknown." (PMID 35571246, 2022). "Moreover, in our in vivo study, the silence of TXNIP markedly decreased the expression level of NLRP3/caspase-1 pathway-related genes and alleviated the damage of the kidney under the sepsis conditions, which is similar with the result of miR-30c-5p treatment." (PMID 32892306, 2021).
Alzheimer disease (18 papers, 2020 to 2024). A progressive, neurodegenerative disease characterized by loss of function and death of nerve cells in several areas of the brain leading to loss of cognitive function such as memory and language. "TXNIP’s involvement in Alzheimer’s disease (AD) is mostly associated with inflammation and accompanied by other processes, such as amyloid β (Aβ) deposition and neurofibrillary tangles." (PMID 34500775, 2021). "TXNIP plays a critical role in cerebrovascular and neurodegenerative diseases, such as subarachnoid hemorrhage and Alzheimer's disease." (PMID 35571246, 2022). "Studies have identified increased TXNIP expression in brains of postmortem AD (Alzheimer’s disease) patients and transgenic AD mice compared to their controls." (PMID 36291328, 2022). "The aim of this study was to identify if cellular expression of TXNIP in human aged and Alzheimer’s disease (AD) brains correlated with pathological structures." (PMID 39483368, 2022). "TXNIP up-regulation sustains neurodegeneration by activating NLRP3 inflammasome, and enhancing the expression of caspase-1 and IL-1β in the brains of Alzheimer's disease patients." (PMID 33509083, 2021).
Hypertension (18 papers, 2013 to 2026). The presence of chronic increased pressure in the systemic arterial system. "A subnetwork with alanine, glutamine, urea cycle (citrulline, arginine), and 1-carboxyethylvaline linked to PFKFB2 and TXNIP revealed associations with kidney function, hypertension and triglyceride metabolism." (PMID 37679740, 2023). "Interestingly, genetic polymorphisms altering TXNIP expression are associated to hypertension, arterial stiffness, and enhanced risk to developing coronary heart disease." (PMID 34827650, 2021). "We speculated that the SNP rs4758685 might be associated with CHD by interacting with hypertension through the TXNIP pathway." (PMID 23840567, 2013). "Despite the presence of a large amount of data describing the involvement of TXNIP and GS in cell responses to pathological factors of various diseases, there is no unambiguous idea of their role in the pathogenesis of myocardial damage caused by a combination of arterial hypertension (AH) and DM." (PMID 37368371, 2023). "Clinical genomic studies have linked variations in TXNIP transcript, elevated BP, arterial stiffness, and coronary heart disease, suggesting that imbalanced ceramide levels and subsequent TXNIP dysregulation may contribute to hypertension." (PMID 38137595, 2023). "This study found that H2S in the PVN improves spontaneous hypertension by inhibiting the PERK/TXNIP/NLRP3 pathway and reducing sympathetic activity." (PMID 41964264, 2026). "Further research is needed to elucidate the specific function, mode of action, and impact of TXNIP on hypertension and ceramide levels." (PMID 38137595, 2023). "The increase in TXNIP expression in hypertension of a longer duration is most likely due to the role of oxidative stress in mediating myocardial cell death in response to ATP deficiency resulting from a hemodynamic overload of the LV." (PMID 37368371, 2023). "In the case of myocardial damage caused by a combination of hypertension and DM, the level of TXNIP and GS was lower than in isolated hypertension or DM, however, it remained higher in comparison with the control group." (PMID 37368371, 2023). "According to the results of the quantitative analysis, in the experimental groups of isolated DM, AH in 57-week-old SHR rats and in the group of combined hypertension and DM, the content of TXNIP in the LV CMC cytoplasm was significantly increased compared with the controls." (PMID 37368371, 2023). "TXNIP, an intracellular inhibitor of the thioredoxin system, is known to participate in the impairment of glucose homeostasis and the etiology of cardiovascular dysfunction, including hypertension." (PMID 35148667, 2022). "Interestingly, differential methylation at multiple genes (SLC7A11, PHGDH, TXNIP, LOC100132354, CPT1A, SLC1A5) is associated with both AC (this study) and with hypertension." (PMID 34857913, 2022). "TXNIP (thioredoxin-interacting protein) emerges as a novel biomarker for ischemia, CVD, and hypertension." (PMID 38137595, 2023). "Collectively, our findings indicated that miR-135a-5p over-expression inhibited TXNIP expression to block the binding of TXNIP and NLRP3, thereby alleviating hypertensive cardiac inflammation and fibrosis." (PMID 35148667, 2022). "Furthermore, rat studies showed that hypertension could also influence TXNIP expression." (PMID 35740021, 2022). "PIK3C2A was notably downregulated in CAD, particularly in ACS, compared to CSA, they discovered, while TXNIP was upregulated in STEMI-ACS patients who were non-diabetic smokers with hypertension and hypercholesterolemia." (PMID 41306139, 2025). "Additionally, we speculated that miR-135a-5p inhibits TXNIP to affect the binding of TXNIP to NLRP3, thus participating in hypertension-induced cardiac fibrosis and inflammation." (PMID 35148667, 2022).
Hypertension (continued). "TXNIP was significantly upregulated in STEMI-ACS patients compared to CSA (p = 0.045) and NSTEMI ACS (p = 0.046), among non-diabetic (p = 0.023) smokers (p = 0.036) with hypertension (p = 0.005) and hypercholesterolemia (p = 0.001)." (PMID 36830671, 2023).
prostate carcinoma (17 papers, 2005 to 2025). A carcinoma that arises from epithelial cells of the prostate gland. "We confirmed the decrease of TXNIP in PCa described in large RNA sequencing studies from four open databases of prostate cancer patients." (PMID 41213907, 2025). "Various studies have shown that TXNIP can play an anticancer role as a tumor suppressor in prostate cancer." (PMID 40149637, 2025). "We functionally validated the direct interaction between AR and the TXNIP promoter by ChIP in prostate cancer cells." (PMID 41213907, 2025). "TXNIP has been reported to be decreased in prostate cancer and to act as a tumor suppressor; in one study, overexpression of TXNIP in PC-3 cells inhibited proliferation, migration, and invasion." (PMID 38396744, 2024). "This is in line with our previous studies demonstrating reduction of TXNIP levels by 1,25(OH)2D3 in prostate cancer cells, as well as the cell line-specific regulation of the protein by treatment." (PMID 30181873, 2018). "Recently, we showed that in the prostate cancer cell line LNCaP, 1,25(OH)2D3 treatment induces diverse metabolic changes that lead to a significant reduction of TXNIP levels." (PMID 29534438, 2018). "Thus, TXNIP expression is downregulated in many tumors, such as breast, lung, hepatocarcinoma, and prostate cancer." (PMID 39526479, 2024). "The enriched genes included CD4 in cervical cancer, VPS52, NUP62, CRYGD, IL34, GATA3 in prostate cancer and F11, TXNIP, KIT, ASGR2, SERPINF1 in liver cancer, which also provide insight into the molecular mechanisms underlying cancer progression and the potential impact on patient survival." (PMID 37393582, 2023). "Similarly, numerous studies have shown that TXNIP inhibits mTOR signaling in prostate cancer and that mTOR signaling inhibition induces TXNIP expression." (PMID 36366411, 2022). "Furthermore, MYC overexpression has been shown to promote thioredoxin interacting protein (TXNIP) suppression in breast and prostate cancer, thus leading to increased glucose uptake to fuel glycolytic metabolism." (PMID 32932943, 2020). "Based on our previous findings in prostate cancer cells, we postulated that 1,25(OH)2D3 could regulate TXNIP expression in HL-60 cells by inducing metabolic changes that stimulate its expression." (PMID 29534438, 2018). "In human prostate cancer, MYC drove glucose metabolism via the suppression of TXNIP (a potent negative regulator of glucose uptake), which was predominantly dependent on the glutaminase-MondoA axis." (PMID 37626036, 2023). "For the BCa cell line MCF7, DASA-58 treatment also strongly reduced TXNIP levels in the prostate cancer cell line LnCap, an effect that was also independent of TXNIP proteasomal degradation." (PMID 33482908, 2021).
pancreatic cancer (16 papers, 2014 to 2024). "The significance of the ATF4/TXNIP/REDD1/mTOR pathway was further supported by associated expressions in xenograft tumors as well as human pancreatic cancer samples." (PMID 38089448, 2022). "To elucidate the role of the tumor suppressor gene TXNIP in thepathogenesis of pancreatic cancer, we initially quantified its expression in a panel ofpancreatic cancer cell lines." (PMID 38229544, 2024). "In vitro experimentswith pancreatic cell lines show that overexpression of TXNIP suppresses the proliferationand migration of pancreatic cancer cells." (PMID 38229544, 2024). "In summary, our findings establish TXNIP as a potential prognostic indicator and treatmenttarget for pancreatic cancer." (PMID 38229544, 2024). "In conclusion, our study reveals TXNIP as a promising new predictivemarker and therapeutic target for pancreatic cancer." (PMID 38229544, 2024). "To evaluate the clinical significance of TXNIP in pancreatic cancer, we examined theexpression status of TXNIP by IHC staining." (PMID 38229544, 2024). "The physiological roles of TXNIP in pancreatic cancer warrantfurther investigation with the aim of enhancing the control of invasion and metastasis andultimately improving the prognosis for this destructive disease." (PMID 38229544, 2024). "Mechanisticstudies are conducted to reveal the role of TXNIP in pancreatic cancer cell proliferation,migration, and regulation during malignancy." (PMID 38229544, 2024). "In pancreatic cancer, elevated TXNIP expression leads to repression of malignant transcripts and impairment of metastatic tumorigenesis through the epigenetic reprogramming of chromatin." (PMID 37794178, 2023). "Several other reports have demonstrated miRNA playing a biological role in pancreatic cancer pathways, such as those targeting TXNIP-Mediated HIF1α, E2F5, TGF-β2/TGF-βRIII, HIF1α, and PTEN." (PMID 35740894, 2022). "MiR-224, another miRNA identified as targeting TXNIP, promotes pancreatic cancer cell proliferation and migration, elevating levels of HIF1α by targeting TXNIP independently of TXN and ROS." (PMID 34199590, 2021). "We propose that PGD-driven suppression of TXNIP allows pancreatic cancers to avidly consume glucose." (PMID 32792504, 2020). "Our data indicate that clonal exchange of TXNIP for PGD supports distant metastasis in pancreatic cancer patients." (PMID 32792504, 2020). "In this study, we investigated the role of TXNIP in pancreatic cancer." (PMID 38229544, 2024). "Thus, in pancreatic cancer, the tumor-suppressive effects of TXNIP do notstem from its inhibition of ROS clearance." (PMID 38229544, 2024). "Collectively, these findings indicated that in vitrooverexpression of TXNIP could attenuate tumorigenic processes in pancreatic cancer cells." (PMID 38229544, 2024). "However, thespecific role and potential mechanisms of TXNIP in pancreatic cancer remain largelyunclarified." (PMID 38229544, 2024). "We subsequently investigated the influence of TXNIP on pancreatic cancer cells." (PMID 38229544, 2024). "The well‐demonstrated role of mTOR signaling in diverse human cancers and its regulation controlled by ATF4‐induced TNXIP‐stabilized REDD1 prompted us to examine the potential involvement of ATF4/TXNIP/REDD1/mTOR signaling in GW3965‐induced biological activities in pancreatic cancer cells." (PMID 38089448, 2022). "TXNIP is a regulator of oxidative stress and has been studied in many diseases such as pancreatic cancer, but how ERS regulates oxidative stress in AP is still unknown." (PMID 35807771, 2022). "Furthermore, we performed an analysis of the mRNA expressions on REDD1, ATF4, and TXNIP from pancreatic cancer samples and the matching normal pancreatic tissues (the Oncomine database)." (PMID 38089448, 2022).
pancreatic cancer (continued). "Further studies using siRNA‐mediated gene silencing showed that ATF4 and TXNIP were essential for GW3965‐induced REDD1 expression, while REDD1 was critical for GW3965‐mediated antiproliferation and pro‐death activities in pancreatic cancer cells." (PMID 38089448, 2022). "More importantly, analysis of human pancreatic cancer samples revealed significant downregulation of ATF4, TXNIP, and REDD1 in the tumor tissues compared to matching normal tissues." (PMID 38089448, 2022). "A reactive oxygen species (ROS) sensor thioredoxin binding protein (TXNIP) and thioredoxin (TXN) were evaluated in pancreatic cancer cells (Panc0403, MiaPaCa2) following treatment with either HNA or 3ETH." (PMID 24952679, 2014). "In pancreatic cancer, the tumor suppressor FBW7 (F-box and WD Repeat Domain-Containing 7) exerts its antitumor effects by controlling glucose metabolism and oxygen consumption in a TXNIP-dependent manner." (PMID 37794178, 2023). "Although their downregulation could be simply a bystander event during pancreatic cancer development, our findings revealed that the upregulations of ATF4, TXNIP, and REDD1 were concomitant with the therapeutic benefits of GW3965." (PMID 38089448, 2022). "Most importantly, we uncovered the significance of ATF4/TXNIP/REDD1/mTOR signaling in the control of the biological activities of GW3965, which was corroborated by expressional analysis on xenograft tumor samples as well as human tissues of pancreatic cancer." (PMID 38089448, 2022). "In pancreatic cancer cells, however, not only was AMPK level or its activation (p‐AMPK) altered by GW3965 treatment but knocking down AMPK by siRNA did not affect REDD1 level in response to GW3965, suggesting the specificity of ATF4 and TXNIP in regulating REDD1 and mTOR in these cancer cells." (PMID 38089448, 2022). "FBXW7 dramatically suppresses glucose metabolism and reduces the 18F-FDG uptake of pancreatic cancer cells through regulating the expression of thioredoxin binding protein (TXNIP) in a c-MYC-dependent manner, whose regulatory mode can be summarized into the FBXW7/c-MYC/TXNIP axis." (PMID 35515121, 2022). "To assess the clinical relevance of our observations, we first compared the mRNA expressions of ATF4, TXNIP, and REDD1 on the basal level between immortalized but nontumorigenic HPNE cells and pancreatic cancer cells." (PMID 38089448, 2022).